LINC00303 (long independently transcribed non-coding RNA 303)
Synonyms: C1orf157; NCRNA00303; FLJ40343
Gene: Long non-coding RNA gene on chromosome 1 (204,032,445 to 204,073,990, reverse strand). Ensembl gene ENSG00000176754.
Diseases named in the same sentence as LINC00303 in open-access papers:
LINC00303 is named in the same sentence as 1 disease in open-access papers, as found by Europe PMC text mining. Sharing a sentence is not in itself a finding about the gene and the disease. The quoted sentences say what the papers report.
cancer (1 paper, 2019). A tumor composed of atypical neoplastic, often pleomorphic cells that invade other tissues. "Additionally, little is known about the regulatory role of AC005609.1, AC068594.1, AC135178.1, AL391832.1, AL445228.2, ATP13A5-AS1, DENND5B-AS1, GRM7-AS3, LINC00303, LMO7-AS1 and NRG1-IT1 in cancer." (PMID 31842887, 2019).